RN7SL513P (RNA, 7SL, cytoplasmic 513, pseudogene)
Gene: Miscellaneous RNA gene on chromosome 19 (18,333,276 to 18,333,573, forward strand). Ensembl gene ENSG00000239821.
Homologues: Orthologues: chimpanzee Metazoa_SRP (99% identical), macaque Metazoa_SRP (94% identical). Paralogues in human: RN7SL1 (84% identical), RN7SL2 (83% identical), RN7SL3 (83% identical), RN7SL296P (80% identical), RN7SL451P (80% identical), RN7SL556P (80% identical), RN7SL797P (80% identical), RN7SL322P (80% identical), RN7SL344P (80% identical), RN7SL732P (80% identical), RN7SL126P (79% identical), RN7SL357P (79% identical), and 703 more.